CRABP2 (cellular retinoic acid binding protein 2)
Diseases named in the same sentence as CRABP2 in open-access papers (continued):
Sharing a sentence is not in itself a finding about the gene and the disease.
ovarian carcinoma (continued). "Furthermore, the positive correlation between CRABP2 and HIF1α protein expression in ovarian cancer tissues, particularly in chemotherapy-insensitive tumors, further supports the clinical relevance of this interaction." (PMID 38195606, 2024). "Our findings suggest that targeting CRABP2 and HIF1α may be a promising strategy for overcoming chemotherapy resistance in ovarian cancer." (PMID 38195606, 2024). "Recent proteomic analyses determined that high levels of CRABP2 are an adverse prognostic marker in estrogen receptor–negative breast tumors, and another study identified CRABP2 to be a subtype-specific biomarker for ovarian cancer." (PMID 38915108, 2024). "Based on the previous experimental results, we wanted to know whether CRABP2 could affect the metabolism of ovarian cancer cells by regulating the expression of HIF1α, ultimately affecting the sensitivity of tumor cells to chemotherapy drugs." (PMID 38195606, 2024). "Importantly, ovarian cancer patients with high expression of both CRABP2 and HIF1α in tumor tissues had the worst prognosis." (PMID 38195606, 2024). "Currently, there is limited research on CRABP2 in ovarian cancer." (PMID 38195606, 2024). "Similarly, the MAP-defined antigens ABCF3 and ANXA2 were also highly expressed across healthy tissues, while CRABP2, although significantly over-expressed in ovarian cancer samples, was expressed at similar or greater levels in several healthy sites." (PMID 36943460, 2023). "Collectively, these results suggest that dezocine might inhibit the expression of CRABP2 by targeting the Akt/mTOR signaling pathway, and ultimately regulate the proliferation and migration of ovarian cancer cells." (PMID 36568517, 2022). "Taken together, CRABP2 might exert an oncogenic role in ovarian cancer and function as a downstream effector of dezocine." (PMID 36568517, 2022). "Our findings based on CRABP2 could advance current practice in diagnosing and treating ovarian cancer." (PMID 35578123, 2022). "CRABP2 could be better in diagnosing ovarian cancer and even separating ovarian cancer and lower malignant tumors such as LMP ovarian tumors and LGSOC." (PMID 35578123, 2022). "The KEGG enrichment analysis results showed that high expression of CRABP2 is related to the activity of oxidative phosphorylation and the tricarboxylic acid cycle, suggesting that CRABP2 may be involved in the metabolic regulation of ovarian cancer cells." (PMID 38195606, 2024). "Moreover, the expression level of CRABP2 mRNA is highest in ovarian cancer metastases." (PMID 38195606, 2024). "Therefore, CRABP2 was a downstream effector of dezocine in ovarian cancer." (PMID 36568517, 2022). "Furthermore, mechanism study showed that dezocine could significantly inhibit the expression of CRABP2, and CRABP2 overexpression reversed the inhibitory effects of dezocine on ovarian cancer cell proliferation and migration." (PMID 36568517, 2022). "CRABP2 was highly expressed in drug-resistant ovarian cancer cells in the database, which made us wonder whether the correlations between CRABP2 higher expression and malignant progression of ovarian cancer and poor prognosis of patients was related to drug resistance." (PMID 38195606, 2024). "Actually, a study has found that the exosome-related CRABP2 is upregulated and promotes cell proliferation in ovarian cancer, and CRABP2 performs better than CA125 in the diagnosis of ovarian cancer." (PMID 38195606, 2024). "One study found that the exosome-related CRABP2 is upregulated and promotes cell proliferation in ovarian cancer, and CRABP2 performs better than the currently used biomarker, CA125, in the diagnosis of ovarian cancer." (PMID 38195606, 2024). "Finally, we identify that CRABP2 is upregulated in ovarian cancer tissues and can be detected at a higher level in the exosome of patients, which might serve as a biomarker and surmount the obstacles in the early diagnosis and targeted therapy of ovarian carcinoma." (PMID 35578123, 2022).
ovarian carcinoma (continued). "CRABP2 can be detected and upregulated in the exosome in ovarian cancer patient serum samples rather than in healthy controls." (PMID 35578123, 2022). "The other two genes, CRABP2 and TNFAIP6, have not been reported as biomarkers of ovarian cancer." (PMID 35578123, 2022).
non-small cell lung carcinoma (13 papers, 2013 to 2025). A group of at least three distinct histological types of lung cancer, including non-small cell squamous cell carcinoma, adenocarcinoma, and large cell carcinoma. "In non-small cells, the plasma CRABP2 concentration in lung cancer patients is significantly higher than that in the normal control group and is associated with a lower survival rate of non-small cell lung cancer." (PMID 34632074, 2021). "Moreover, CRABP2, as a diagnostic and targeting biomarker, has been studied in a large number of carcinomas, for instance, the prostate cancer, the head and neck tumors, the primary retinoblastoma tumors, the non-small cell lung cancer and the Wilms tumors." (PMID 26839961, 2016). "The overexpression of CRABP2 has been reported in tumor tissues of non-small cell lung cancer (NSCLC)." (PMID 38915108, 2024). "I In addition, CRABP2 promotes lung cancer cell metastasis through HuR and integrin β1/FAK/ERK signaling, and plasma CRABP2 is being used as a novel biomarker in patients with non-small cell lung cancer." (PMID 38195606, 2024). "It has been reported that the abnormal expression of CRABP2 is closely related to the development of neuroblastoma, Wilms tumor, head and neck squamous cell carcinoma, and non-small-cell lung cancer." (PMID 36195596, 2022). "Furthermore, in non-small cell lung cancer, kidney cancer, and glioma, elevated expression of CRABP2 was substantially related to a poor tumor prognosis." (PMID 38915108, 2024). "In non-small cell lung cancer cells, inhibition of CRABP2 may inhibited the NF-κB pathway, leading to a decrease in EMT of tumor cells." (PMID 38186580, 2023). "Testing the plasma CRABP2 concentration may be a new genetic testing method for the diagnosis of non-small cell lung cancer and the prognosis." (PMID 34632074, 2021). "Here we also found that the expression of CRABP2 in human lung tumors was correlated with stress marker CHOP, which was reported to be correlated with lymph node metastasis of non-small cell lung cancer patients." (PMID 30696915, 2019). "CRABP2 is extensively connected in the development of neuroblastoma, Wilms tumor, head and neck squamous-cell carcinoma (HNSCC), and non-small cell lung cancer (NSCLC)." (PMID 31419991, 2019).
lung carcinoma (12 papers, 2019 to 2025). "Four studies reported the association between the elevated plasma level of CRABP2 and OS in lung cancer." (PMID 38915108, 2024). "The recent discovery of CRABP2 and the exploration of the associated mechanisms have resulted in great advances in the area of lung cancer." (PMID 38915108, 2024). "As Crabp2 is overexpressed in high-metastatic C10F4 cells, and is correlated with tumor progression of lung cancer patients, we further evaluated the association of CRABP2 with prognosis and recurrence of lung cancer patients." (PMID 30696915, 2019). "Taking all these into consideration, the presence of elevated CRABP2 expression in lung cancer patients may be have a significant risk factor for poor prognostic factor for overall survival." (PMID 38915108, 2024). "In addition, CRABP2 expression is associated with poor survival and recurrence in lung cancer patients." (PMID 37004157, 2023). "Our meta-analysis included 4 studies, indicating that the elevated plasma level of CRABP2 significantly predicted poor OS (HR: 1.14 (95% CI: 1.00–1.30) in lung cancer patients." (PMID 38915108, 2024). "Based on our results, this meta-analysis shown that the elevated CRABP2 expression significantly predicted poor OS in patients suffering from lung cancer." (PMID 38915108, 2024). "CRABP2 has been documented to facilitate metastasis in lung cancer by activating the ERK signaling pathway." (PMID 38267624, 2024). "In lung cancer, Crabp2 expression is elevated in highly metastatic mouse lung cancer cells compared to less metastatic counterparts, facilitating integrin β1/FAK/ERK signaling." (PMID 39768218, 2024). "There were 2 studies showing the data of association between the CRABP2 and PFS in lung cancer patients." (PMID 38915108, 2024). "The findings from these studies were taken into consideration in order to outline the criteria for exploration and explanation of the connection between CRABP2 and its prognostic value in lung cancer patients." (PMID 38915108, 2024). "This study investigated the prognostic role of CRABP2 in lung cancer from the perspective of 2 survival indicators: OS and PFS." (PMID 38915108, 2024). "The obtained results suggested that increased plasma level of CRABP2 predicted poor OS in lung cancer patient with a combined HR of1.14 (95% CI: 1.00–1.30)." (PMID 38915108, 2024). "The prognostic value of cellular retinoic acid-binding protein 2 (CRABP2), in lung cancer patients remains to be uncertained." (PMID 38915108, 2024). "As a result, we intend to conduct a meta-analysis to comprehensively and systematically understand the prognostic value of CRABP2 in lung cancer patients." (PMID 38915108, 2024). "Two studies illustrated the association between the elevated plasma level of CRABP2 and PFS in lung cancer." (PMID 38915108, 2024). "We also explored the potential upstream regulating factors leading to the upregulation of Crabp2 in lung cancer cells." (PMID 30696915, 2019). "Higher CRABP2 levels were also found to be correlated with decreased patients’ survival in three cohorts of lung cancer tissues." (PMID 30696915, 2019). "In this study, Crabp2 was overexpressed in high-metastatic C10F4 than low-metastatic lung cancer cells." (PMID 30696915, 2019). "Although Crabp2 is found to be overexpressed in lung cancer, its role in metastasis of lung cancer is unclear." (PMID 30696915, 2019). "Together, our results for the first time identified the metastasis-promoting role of Crabp2 in lung cancer." (PMID 30696915, 2019). "High CRABP2 levels were correlated with advanced stages, poor overall survival, and recurrence of lung cancer patients." (PMID 30696915, 2019). "Using blood buffy coat samples from lung cancer patients (n = 48), our results showed significantly higher CRABP2 levels in patients with advanced lymph node metastasis (N2-3) than those having none or early lymph node metastasis (N0-1) (p = 0.0089)." (PMID 30696915, 2019).
lung carcinoma (continued). "Multiple cohorts of lung cancer patients were analyzed to reveal the correlation of CRABP2 with tumor progression and clinical outcomes." (PMID 30696915, 2019). "In the present study, we found that Crabp2 was upregulated in lung cancer cells with enhanced metastasis." (PMID 30696915, 2019). "In conclusion, this is the first study to demonstrate the role of Crabp2 in metastasis of lung cancer." (PMID 30696915, 2019). "Overall, our findings reveal the promoting role of Crabp2 in migration, invasion, anoikis resistance, and metastasis of lung cancer." (PMID 30696915, 2019). "The present study was conducted to assess the prognostic value of CRABP2 in lung cancer." (PMID 38915108, 2024). "Currently, only a few studies are available on the role of CRABP2 in lung cancer." (PMID 38915108, 2024). "Therefore, our research attempted to assess the relationship between CRABP2 and survival analysis in lung cancer patients through meta-analysis." (PMID 38915108, 2024). "Combinatorial treatment of retinoids with EGFR-TKIs drugs in EGFR-TKIs resistance lung cancer cells promotes the activation of GATA6 and then inhibits the activation of EGFR/Wnt signaling pathways and favors the association of RXR, RARβ, and cellular retinoic acid binding protein-2 (CRABP2)." (PMID 32293355, 2020). "Crabp2 might be a potential prognostic biomarker for lung cancer and a therapeutic target to inhibit metastasis and enhance the inhibitory effects of gemcitabine and irinotecan in metastatic lung cancer cells." (PMID 30696915, 2019). "We identified the promoting role of Crabp2 in metastasis of lung cancer cells." (PMID 30696915, 2019). "Our results suggest that Crabp2 may be part of the mechanism regulating migration, invasion, and anoikis resistance in lung cancer cells." (PMID 30696915, 2019). "We next explored the correlation of CRABP2 levels with tumor progression of lung cancer patients." (PMID 30696915, 2019). "The prognostic value of CRABP2 in lung cancer patients is still unknown." (PMID 38915108, 2024). "However, the role of CRABP2 in lung cancer is still unclear." (PMID 38915108, 2024). "CRABP2 could be a useful prognostic biomarker and a target against lung cancer metastasis." (PMID 30696915, 2019). "However, the role of Crabp2 in metastasis of lung cancer is still unclear." (PMID 30696915, 2019). "In the present study, we found that Crabp2 activated integrin β1/FAK/ERK signaling via HuR, and thus promoted migration, invasion, and anoikis resistance of metastatic lung cancer cells." (PMID 30696915, 2019). "Similar to CRABP2, CHOP is overexpressed in lung tumors, and is correlated with poor survival and increased recurrence of lung cancer patients." (PMID 30696915, 2019). "However, the role of Crabp2 in metastasis of lung cancer has not been investigated until this study." (PMID 30696915, 2019). "At present, the role of Crabp2 in metastasis of lung cancer has not been investigated." (PMID 30696915, 2019).
glioblastoma (7 papers, 2018 to 2025). The most malignant astrocytic tumor (WHO grade IV). "CRABP2 is localized in glioblastoma, and sequestration of RA in the cytoplasm has been reported to enhance cell proliferation." (PMID 37004157, 2023). "Reports showed that CRABP2 promoted proliferation of glioblastoma and malignant peripheral nerve sheath tumor cells." (PMID 30696915, 2019). "In glioblastoma tumors, CRABP2 were found to correlate with poor patient survival." (PMID 30696915, 2019). "In the first, CRABP2 knockdown sensitized glioblastoma cells to retinoic acid induced apoptosis." (PMID 29880835, 2018).
lung adenocarcinoma (7 papers, 2019 to 2025). A carcinoma that arises from the lung and is characterized by the presence of malignant glandular epithelial cells. "Further analysis will be needed to determine whether CRABP2 is involved in RA function or has other roles in lung adenocarcinoma." (PMID 37004157, 2023). "Similarly, siRNA of CRABP2 reduced the migration and invasion of metastatic human lung adenocarcinoma H1650 cells." (PMID 30696915, 2019). "However, there are few comprehensive analysis studies on CRABP2 in lung adenocarcinoma (LUAD)." (PMID 39991584, 2025). "Furthermore, CRABP2, DHCR24, and AK4 are useful IHC markers for diagnosis of lung adenocarcinoma invasiveness and may be associated with malignant progression of AIS." (PMID 37004157, 2023). "In our research, we conducted a comprehensive analysis by collecting plasma samples from patients with lung adenocarcinoma (LUAD) and quantified the levels of Cellular Retinoic Acid Binding Protein 2 (CRABP2)." (PMID 39991584, 2025). "Expression of CRABP2, DHCR24, and AK4, and clinicopathological features in patients with lung adenocarcinoma." (PMID 37004157, 2023). "Among them, CRABP2, KAT2A, BIRC5, ABCC3, PLK1, IGHG1, and EPCAM were upregulated in lung adenocarcinoma samples, while FABP4 was downregulated in lung adenocarcinoma samples." (PMID 35909589, 2022).
pancreatic cancer (7 papers, 2020 to 2025). "CRABP2 promotes the invasion and metastasis of pancreatic cancer cells, and inhibiting the expression of CRABP2 can inhibit the migration of cancer cells." (PMID 36195596, 2022). "The role of CRABP2 and NUSAP1 in pancreatic cancer is currently unclear, but CRABP2 and NUSAP1 favors proliferation and invasion of several types of tumor, such as prostate, lung, gastric and colorectal cancer." (PMID 33748143, 2021). "Abnormal CRABP2 expression is associated with numerous cancers, including non-small cell lung cancer (NSCLC), pancreatic cancer and serous ovarian cancer." (PMID 32927694, 2020). "Based on the transcriptomics profiling of anlotinib in this work and available pancreatic cancer related data deposited in TCGA, GEO, and ICGC databases, we further constructed a prognostic model which consists of five crucial genes, namely TOP2A, CRABP2, CDK1, NUSAP1, and PERP." (PMID 33748143, 2021).
Wilms tumor (7 papers, 2011 to 2023). An embryonal neoplasm characterized by the presence of epithelial, mesenchymal, and blastema components. "In some cancers, such as Wilms tumors, the pattern is reversed and a poor outcome is associated with high CRABP2." (PMID 35796328, 2023). "CRABP2 protein expression has been observed in human fetal kidney samples during mesenchymal-epithelial transition and in the blastemal component of nephroblastoma; in the latter, the RA pathway was found to be associated with CRABP2 upregulation." (PMID 29378601, 2018). "In Wilms tumor, the expression of CRABP2 is increased in samples of patients receiving preoperative chemotherapy and patients with metastatic disease." (PMID 34632074, 2021). "Immunopositivity for RARA and CRABP2 was observed in all three histological components of nephroblastoma (blastema, stroma, and epithelium)." (PMID 29378601, 2018). "The present work is the first report of the evaluation of RARA and CRABP2 immunoexpression as potential biomarkers and therapeutic targets in nephroblastomas." (PMID 29378601, 2018). "In conclusion, semiquantitative and quantitative analyses of the markers RARA and CRABP2 indicate these proteins as potential biomarkers of tumor progression and their participation in nephroblastoma tumorigenesis." (PMID 29378601, 2018). "The findings of these authors indicate the role of CRABP2 in cell migration and invasion in nephroblastomas." (PMID 29378601, 2018). "The results obtained by quantitative analysis of RARA and CRABP2 expression in the nephroblastoma samples showed median values of 24.2% per HMF (6.3%–40.3%) and 26.3% per HMF (4.2%–40.4%), respectively." (PMID 29378601, 2018). "This study aims to evaluate the distribution of RARA and CRABP2 protein expression and positivity in nephroblastoma tissue specimens and to correlate these results with clinical and pathological prognostic factors." (PMID 29378601, 2018). "Semiquantitative and quantitative analyses of the markers RARA and CRABP2 indicate their potential as biomarkers for tumor progression and their participation in nephroblastoma tumorigenesis." (PMID 29378601, 2018). "Upregulation of CRABP2 has been reported in the blastema of nephroblastomas during the investigation of genes related to nephrogenesis." (PMID 29378601, 2018). "Another study by Gupta and colleagues revealed increased expression of CRABP2 in late stage Wilms tumors." (PMID 22067876, 2011). "CRABP2 immunoexpression: C, renal parenchyma; D, nephroblastoma (40×)." (PMID 29378601, 2018). "The aim of this study was to evaluate the immunohistochemical expression of retinoic acid receptor alpha (RARA) and CRABP2 in paraffin-embedded samples of nephroblastomas via semiquantitative and quantitative analyses and to correlate this expression with prognostic factors." (PMID 29378601, 2018).